NLRP3 (NLR family pyrin domain containing 3)
Diseases named in the same sentence as NLRP3 in open-access papers (continued):
Sharing a sentence is not in itself a finding about the gene and the disease.
asthma (continued). "NLRP3 (NOD-like receptor family pyrin domain containing 3), as an immune sensor of cellular stress, is closely related to the development of asthma." (PMID 38274803, 2023). "We previously showed that increased IL-1β responses drive steroid-insensitive, inflammation and AHR, and that inhibiting NLRP3 activation with MCC950 reduced IL-1β production and ablated these features in murine models of severe asthma." (PMID 38044426, 2023). "In contrast, this study regarded NLRP3 inflammasome activation as an initiation of pyroptosis and revealed the downregulation effect of MUC1 on pyroptosis in asthma." (PMID 37880668, 2023). "Herein, we investigated the regulation of DEK on the PINK1-Parkin pathway, NLRP3 inflammasome, and apoptosis in the HDM-induced asthma model." (PMID 38274803, 2023). "Based on these previous findings and our findings, we conclude that PINK1-Parkin-mediated mitophagy can promote NLRP3 inflammasome pathway activation and apoptosis in HDM-induced asthma." (PMID 38274803, 2023). "We discuss the complex relationship between NLRP3 inflammasomes and inflammatory responses found in animal models, asthma and COPD patients, to prove that inflammasome plays a key role in asthma and COPD inflammation." (PMID 36444628, 2022). "Previous studies have shown that activation of NLRP3 inflammasome is observed in HDM and fungi-induced asthma, and NLRP3 inflammasome inhibition mitigates asthmatic symptoms such as Th2 cytokine release, airway hyperresponse, and inflammatory responses." (PMID 36432032, 2022). "Therefore, we are devoted to exploring the effects of CAD on pyroptosis and the TLR3/NLRP3/NF-κB/IRF3 signaling pathway in OVA/RSV-induced asthma mouse models, which may contribute to promoting understanding of CAD in the treatment of acute asthma with RSV infection." (PMID 36213326, 2022). "The function of NLRP3 and MAVS needs to be confirmed by further research and it is helpful to deeply understand asthma." (PMID 36595748, 2022). "NLRP3 inflammasome is suggested as a potential therapeutic target to attenuate severe RSV disease and limit childhood asthma development." (PMID 35308390, 2022). "A recent research found that inhibiting the NLRP3 inflammasome reduced AHR and airway inflammation in a steroid-resistant asthma mouse model." (PMID 35664352, 2022). "Besides, more detailed basic and clinical investigations through systemic inhibition studies such as knock-down or knock-out models are required to assess whether overexpression of TLR3/NLRP3/NF-κB/IRF3 signaling could reverse the protective effect of CAD on asthma." (PMID 36213326, 2022). "NLRP3 has been reported to regulate M2 macrophage polarization through interaction with IRF4 and the upregulation of IL-4 in asthma." (PMID 34413860, 2021). "NLRP3 promoted airway inflammation and pathogenesis in an inflammasome-dependent manner in HDM-induced asthma." (PMID 34413860, 2021). "Mechanistically, active NLRP3 inflammasome in epithelial cells activate caspase‐1 to cleave GSDMD, finally increasing the IL‐1β release and aggravating the airway inflammation in asthma." (PMID 34590363, 2021). "This is the first report on the role of BLT1/2 in the regulation of NLRP3 stimulation and IL-1β synthesis in a neutrophilic airway inflammation mouse model, and our results may provide a perspective for the development of treatments for asthma patients with steroid resistance." (PMID 34064821, 2021). "Therefore, the role of the NLRP3 inflammasome in the regulation of asthma also remains unknown." (PMID 34413860, 2021). "NLRP3 activation induces IL-1β secretion primarily by M1 macrophage, which induces AHR that is considered as a major feature of asthma." (PMID 30050954, 2018). "Meanwhile, the protein levels of NLRP3, ASC, Caspase-1 and Pro-Caspase-1 in lung tissue of YPFS treated OVA-sensitized asthma mice also decreased significantly in comparison with those in model group." (PMID 29311942, 2017).
asthma (continued). "Western blot analyses showed that the levels of NLRP3 and caspase-1 in BAL fluids from the patients with asthma were significantly higher than the levels in healthy subjects." (PMID 25356867, 2014). "Pharmacological blockade of NLRP3 using inhibitors such as MCC950 reduces airway inflammation in murine models of allergic asthma, positioning it as a therapeutic target for Th2-high asthma." (PMID 41394843, 2025). "Our study showed that the ZLN005 reduced NLRP3 protein expression and IL-18 and IL-1β mRNA levels, suggesting that ZLN005 could alleviate asthma by inhibiting inflammasome activation." (PMID 40343297, 2025). "NLRP3 has a role in pediatric asthma (especially non-allergic or steroid-resistant asthma) with increased serum levels along with IL-1β, and their level in induced sputum positively correlates with the severity of the disease." (PMID 41318536, 2025). "The inhibition of NLRP3, a critical component of the innate immune system known to drive steroid‐resistant neutrophilic inflammation in severe asthma, positions BBR as a potential agent for managing difficult‐to‐treat asthma phenotypes." (PMID 41473388, 2025). "PGC-1α agonist (ZLN005) regulated lung inflammation in asthmatic mice by inhibiting the NF-κB-p65/NLRP3 signaling pathway, supporting that ZLN005 may be a candidate for future asthma treatment." (PMID 40343297, 2025). "Moreover, use of specific NLRP3 inflammasome inhibitors reduced HDM-induced AHR and attenuated steroid-resistant asthma in a mouse model." (PMID 38811424, 2024). "Higher expression of NLRP3 and higher levels of IL-1β and IL-18 from severe asthma group in non-stimulated state.Significant increase of IL-1β and IL-18 after NLRP3 activation." (PMID 39554494, 2024). "In line with that, we did not detect the expression of NLRP3 protein in differentiated HBECs from controls and patients with asthma at baseline or after RV infection." (PMID 37087523, 2023). "We first assessed the response of PBMCs from healthy subjects and patients with severe and non-severe asthma to NLRP3 inflammasome-induced IL-1β release." (PMID 38044426, 2023). "MUC1-CT reduces NLRP3 inflammasome-mediated pyroptosis by inhibiting the activation of the TLR4/MyD88/NF-κB pathway, thereby attenuating neutrophil airway inflammation in patients with asthma." (PMID 37880668, 2023). "We also show that systemic immune cells from patients with severe asthma release more IL-1β following a combination of pathogen (LPS)-induced priming and NLRP3 inflammasome activation compared to cells from patients with non-severe asthma." (PMID 38044426, 2023). "Mechanistic studies revealed that MUC1 reduced NLRP3 inflammasome-mediated pyroptosis by inhibiting TLR4/MyD88/NF-κB pathway activation, thereby suppressing neutrophilic airway inflammation in patients with asthma." (PMID 37880668, 2023). "Furthermore, in murine models of asthma induced by OVA or house dust mite (HDM), blocking NLRP3 with specific inhibitor or gene knockout mice significantly alleviated asthma symptoms." (PMID 35664352, 2022). "On the contrary, above the critical concentration of ApoE could activate NLRP3 inflammasome and induce BALF macrophages in patients with asthma to secrete mature IL‐1 β, which further magnified pulmonary inflammatory response." (PMID 36444628, 2022). "Besides, increased mRNA expression of inflammasome sensors (NLRP1, NLRP3, and NLRC4) and increased cytokine IL-1β levels are observed in the sputum samples of patients with neutrophilic severe asthma." (PMID 36248872, 2022). "For this reason, NLRP3 which regulates pyroptosis-induced asthma requires to be further studied, and TLR3/NLRP3/NF-κB/IRF3 signaling inhibition could be an anti-inflammatory strategy in airway epithelial injury." (PMID 36213326, 2022). "Furthermore, NLRP3 inhibition resulted in AHR reduction, decrease of asthma histopathological features, and suppression of Th2 and Th17 responses." (PMID 36189256, 2022).
asthma (continued). "It was found that saturated fatty acid diet significantly increased the 4 h percentage of neutrophils in sputum and the gene expression of TLR4 and NLRP3 in nonobese asthma patients compared with those measured at 0 h." (PMID 36444628, 2022). "Although the exact role of pyroptosis activation in the experimental animal models of asthma is not completely clear, the key complexes such as NLRP3, GSDMB, GSDME, etc., and related signaling pyroptosis pathways are still promising therapeutic strategies." (PMID 36248872, 2022). "Generally, these results indicated that apoptosis and pyroptosis played an important role in RSV-infected asthma mice and LPS-mediated 16HBE cells, and CAD potential inhibits the TLR3/NLRP3/NF-κB/IRF3 signaling pathway and subsequently suppresses airway inflammation and pyroptosis." (PMID 36213326, 2022). "In addition to the NLRP3 inflammasome, a very recent study evaluated the role of the RIG-I inflammasome in respiratory viral infection, including RV and SARS-CoV-2, in asthma." (PMID 36077310, 2022). "Pyroptosis may be involved in inflammation-related respiratory diseases such as asthma, COPD, lung cancer, ALI, silicosis, PH, and TB, in which the NLRP3 inflammasome-induced pathway is mostly highlighted." (PMID 35819638, 2022). "Further experiments then showed that similar to in human monocytes, asthma in mice is driven by NLRP3 but this relationship does not involve ASC or caspase-1." (PMID 35743263, 2022). "Furthermore, the development of AHR in obesity-related asthma in mice relied on IL-17-producing ILC3s and the NLRP3 inflammasome, and ILC3s were expanded in the BAL of severe asthma patients." (PMID 34630416, 2021). "In humans, both IL-1 receptor and NLRP3 inflammasome are elevated in the sputum of non-smoking adults with asthma." (PMID 32194407, 2020). "A second important area that requires future research is the discrimination between different diseases phenotypes; e.g., eosinophilic, neutrophilic, paucigranulocytic asthma and the involvement of different target such as PARP-1 and NLRP3 in the determination of these phenotypes." (PMID 32509795, 2020). "Interestingly, a recent report demonstrated that NLRP3, along with IRF4, transactivates the Il4 promoter, enhances Th2 cell differentiation, and exacerbates asthma symptoms in a mouse model." (PMID 31590215, 2019). "Above all, our data here showed that Andrographolide can inhibit OVA-induced asthma with a possible mechanism of ROS elimination, thus negatively regulate NF-κB and NLRP3 inflammasome activation and attenuate lung inflammation/injury in mice." (PMID 27793052, 2016). "Activation of the NLRP3 inflammasome in the lungs not only facilitates the infiltration and activation of neutrophils, but also promotes the expansion and activation of ILC3s and IL17A secretion, which contribute to exacerbated asthma symptoms and increased steroid resistance." (PMID 40329860, 2025). "However, eosinophilic airway inflammation remained similar across genotypes, suggesting that this aspect of asthma pathophysiology is independent of NLRP3 expression." (PMID 41394833, 2025). "In contrast, other studies in different mouse models have suggested that NLRP3 may not play a significant role in acute or chronic asthma." (PMID 41394833, 2025). "Distinguishing these pathways will be crucial when considering NLRP3-targeted strategies in asthma, since barrier-stabilizing effects may not solely reflect inflammasome inhibition but also loss of homeostatic epithelial functions of NLRP3." (PMID 41394833, 2025). "Given the established significance of these pathways in asthma-related inflammation, the aim of our study was to determine whether GLCCI1 modulates airway inflammation through its involvement in the PI3K pathway and in NLRP3 inflammasome activation." (PMID 39834584, 2024).
asthma (continued). "However, the blockade of the NLRP3/caspase-1 axis attenuated the bronchial neutrophilic inflammation in mice exposed to toluene diisocyanate (TDI), implying that the NLPR3/caspase-1 signaling promotes neutrophilic inflammation in asthma." (PMID 39611173, 2024). "In another study, the inactivation of transcription factor EB, a major regulator of autophagy, can activate the mTORC1 signaling pathway in circulating monocytes from patients with severe asthma, and thus autophagy is impaired in this process and fails to inhibit NLRP3-driven inflammatory responses." (PMID 37181813, 2023). "However, OS biomarkers NO2−, lipid peroxide, protein sulfhydrils, and inflammatory biomarkers TNFα, IL-4, IL-37, IL-1β, IL-1RL1, IL-1R1, NLRP3, and TGF-β1 showed positive association with asthma in nonsmokers, but not in smokers." (PMID 37367073, 2023). "Another study indicated that silica nanoparticles aggravate airway inflammation and asthma development by increasing the protein expression levels of thioredoxin-interacting protein (TXNIP) and the NOD-like receptor pyrin domain-containing 3 (NLRP3) inflammasome." (PMID 35936002, 2022). "Pyroptosis may be involved in asthma, chronic obstructive pulmonary disease (COPD), lung cancer, acute lung injury (ALI), silicosis, pulmonary hypertension (PH), and tuberculosis (TB), in which the NLRP3 inflammasome-induced pathway is mostly highlighted." (PMID 35819638, 2022). "There is no clear conclusion on how NLRP3 inflammasomes are activated in asthma." (PMID 36444628, 2022). "Importantly, although most of the attention regarding a potential role for NLRP3 in asthma has been directed to myeloid cells and the lung epithelium, the relevance of NLRP3 in the asthma context is not restricted to neutrophilic responses and phenotypes." (PMID 36189256, 2022). "Additionally, CAD and CAD-contained serum attenuated the up-regulated expressions of Bax, Cleaved caspase-3, NLRP3, ASC, Cleaved caspase-1, GSDMD-N, IL-18, IL-1β, TLR3, p-P65, p-IκBα, and IRF3 but increased Bcl-1 and GSDMD levels in the asthma mice and LPS-induced 16HBE cells, respectively." (PMID 36213326, 2022). "The expression of NLRP3 was not changed in alveolar macrophages, neutrophils or dendritic cells, but was increased in asthmatic lungs because the percentage of inflammatory cells was upregulated during asthma (F and Supplementary 2A)." (PMID 34413860, 2021). "Increased expression of NLRP3 and IL-1β was also detected in the sputum of patients with SA compared to MMA, and correlated with clinical parameters of disease, such as neutrophilic airway inflammation, Asthma Control Questionnaire (ACQ) score, and Forced Expiratory Volume in 1 second (FEV1)%." (PMID 31590215, 2019). "Therefore, our results suggested that the activation of NLRP3 promoted asthma, and its effect was unlikely to rely on NLRP3 inflammasome activation." (PMID 30363922, 2018). "Interestingly, previous studies had shown the anti-inflammatory function of MUC1 in asthma, by reducing the NLRP3 inflammasome-mediated pyroptosis through the inhibition of the TLR4/MyD88/NF-κB pathway, thereby suppressing neutrophilic airway inflammation in patients with asthma." (PMID 41295249, 2025). "Importantly, we demonstrate here that naïve NLRP3-/- mice exhibit intrinsic defects in tight junction expression and E-cadherin levels, leading to increased allergen uptake, a baseline phenotype not previously reported in asthma models." (PMID 41394833, 2025). "An deficiency of GLCCI1 in macrophages significantly reduced the ability of LY294002 to suppress NLRP3-mediated inflammation, reinforcing the idea that a signaling pathway involving PI3K, GLCCI1, and NLRP3 may shape macrophage function in the context of asthma." (PMID 39834584, 2024). "Importantly, we highlight that NLRP3 inflammasome-mediated IL-1β responses can be therapeutically suppressed in systemic immune cells from patients across all subtypes of both severe and non-severe asthma." (PMID 38044426, 2023).
asthma (continued). "Bruchard and colleagues demonstrated that NLRP3 expression in CD4+ T cells specifically supported Th2 transcription in a cell-intrinsic manner, and the ability of NLRP3 to control Th2 polarization was involved in the promotion of asthma, independent of inflammasome activation." (PMID 30363922, 2018).